MUC1 (mucin 1, cell surface associated)
Diseases named in the same sentence as MUC1 in open-access papers (continued):
Sharing a sentence is not in itself a finding about the gene and the disease.
tumor (continued). "The surface-binding property of the sugar may confer an evolutionary advantage for the host considering the heterogeneous nature of the glycosylation of tumor-specific MUC1 protein, where the antibodies can be selected and evolved faster in the maturation process." (PMID 29857542, 2018). "Many of the MUC1-reactive antibodies reacted with peptide sequences in the TR domain, and the concept arose that in the cancer mucin, with shorter glycan chains, some of these peptide sequences were more exposed, thus explaining the tumour specificity of antibodies such as SM3 and DF3-P." (PMID 29784646, 2018). "Some of these new antibodies show specificity for the tumour MUC1 glycoforms and humoral and cellular immune responses to one vaccine formulation (1TR carrying Tn and STn bound to tetanus toxin) have been detected in MUC1 transgenic mice where human MUC1 is expressed from the MUC1 promoter." (PMID 29784646, 2018). "Thus, the newly identified MUC1-p65-EzH2 axis might create the favorable microenvironment for tumor initiation and progression." (PMID 29285251, 2017). "The tumor form of MUC1 also creates a different landscape of inflammatory cells in the tumor microenvironment by controlling the recruitment of inflammatory cells, establishing specific interactions with dendritic cells (DCs) and macrophages, and facilitating tumor escape from the immune system." (PMID 27754373, 2016). "Curiously, Mucin-1 (MUC-1) serves as the E-selectin ligand in these cells but also enables firm adhesion by binding to intracellular adhesion molecule-1 (ICAM-1) suggesting that selectin scaffolds may have more than one role during tumor extravasation." (PMID 27148485, 2016). "The diversification of the immune response and the intramolecular epitope spreading may obviate the need for development of custom vaccines for different glycoforms of MUC1 which arise among patients with tumors originating from different tissues or even within the same tumor type." (PMID 26788922, 2016). "In this study, a tumor-targeting aptamer was coupled to a DNA Td to form the Apt-Td, which not only had a significantly higher drug-loading capacity (25-fold) compared to a free MUC1 aptamer, but also selectively delivered the drug to MUC1-positive cancer cells." (PMID 27203221, 2016). "In contrast to the majority of the established endocrine PDTXs, tissue-derived MUC-1 xenografts were characterized by the engraftment of large solid tumors and the maintenance of pathological and endocrine features comparable to that of the original patient tumor." (PMID 27764813, 2016). "Transfection of the cDNA of MUC1-TRIM46-KRTCAP2 isoforms in mammalian cells led to the translation of mutant MUC1 fusion proteins that are unglycosylated and cytoplasmically localized as opposed to the cell membrane, a feature resembling the tumor-associated MUC1." (PMID 26492273, 2015). "Moreover, MUC1-TRIM46-KRTCAP2 fusion isoforms are unglycosylated and localized in the cytoplasm as opposed to the cell membrane, a feature resembling tumor-associated MUC1." (PMID 26492273, 2015). "Moreover, this vaccination can prevent tumor growth and reduce tumor burden in MUC1+B16 mice model." (PMID 26417929, 2015). "Our previous study found that MUC1 gene silencing decreased Smad3 mRNA level in HCC cells, and another study has shown that MUC1 can active JNK to inhibit cell apoptosis, thus leading to the hypothesis that MUC1 shifts Smad3 from tumor-suppression to oncogenesis by activating JNK in HCC cells." (PMID 25714018, 2015). "This is confirmed by the support of the presence of several tumor associated antigens in the prostate; which include the PSA, prostatic acid phosphatase (PAP), prostate specific membrane antigen (PSMA), prostate stem cell antigen (PSCA), mucin-1 (MUC-1), and the cancer testis antigen NY-ESO-1." (PMID 26161414, 2015).
tumor (continued). "Apart from revealing the inhibitory effects of BR/NAC on tumor growth, this animal study also indicated, consistent with our in vitro observations, that BR/NAC therapy remarkably diminished the tumor production of the membrane-associated mucin MUC1, as well as of the secreted mucins MUC2 and MUC5AC." (PMID 26436698, 2015). "The highly expressed MUC1 could play an important role in tumor infiltration and metastasis." (PMID 25136635, 2014). "Hence, targeting MUC-1 could have a dual role – directing the immune response toward the tumor and reducing immune suppression." (PMID 24834066, 2014). "Indeed, in healthy cells MUC1 contains extended, core 2-based glycans that are formed by N-acetylglucosamine attachment to the GalNAc of core 1, while on the MUC1 expressed by tumor cells the glycans are shorter, core 1-based and richer in ST, Tn, and T glycans." (PMID 23509794, 2013). "Thus, we used the MUC1 and HLA-A2 positive tumor cell line, PANC-1." (PMID 23717436, 2013). "As a consequence, tumor cell proliferation could be supported by increasing number of Treg cells, which potentially underwent expansion in MUC1.Tg mice in accordance with proliferation of tumor cells expressing MUC1." (PMID 23028615, 2012). "Since MUC1 is over expressed in several types of cancers and its over-expression is correlated with poor prognosis and increased cell invasion and metastasis, vaccination with the mimic peptides may therefore be useful in preventing metastasis of MUC1-overexpression tumours." (PMID 23166757, 2012). "The fact that the vast majority of MCF7 stem cell enriched SP cells express MUC1 suggests that epithelial cancer stem cells would also be the targets of various immunotherapy approaches based on the MUC1 tumor antigen that has been designed with mature tumor cells in mind." (PMID 21521521, 2011). "Abs bound to the (glyco)peptide or glycan epitopes on MUC1-N may restore cell-cell interaction and prevent tumor progression by inducing capping or clustering of MUC1 and exposing cell adhesion molecules covered by MUC1, as observed in vitro with MAbs to the MUC1 TR." (PMID 24212946, 2011). "However, using siRNA we found that down-regulation of MUC1 failed to significantly affect either the intrinsic Δψm or the tumor phenotypes associated with increased intrinsic Δψm." (PMID 21966455, 2011). "Therefore to investigate if the use of a single glycoprotein carrying STn could also induce tumour protection, we selected MUC1-carrying STn as an immunogen." (PMID 19436292, 2009). "Therefore, DCs/tumor fusion-based vaccine may represent an effective strategy to induce antitumor immunity, including MUC1-positive tumor cells." (PMID 20182533, 2009). "In addition, circulating immune complexes levels were statistically associated with tumor size, inversely associated with MUC1 tumor expression and were not positively associated with serum MUC1 and free anti-MUC1 IgG." (PMID 17064405, 2006). "It is difficult to determine whether the difference in the outcomes between that study and ours is due to a real difference between loading DCs with whole tumor cells and loading them with tumor cell lysate, or to a difference in how the MUC-1 specific T cells were detected." (PMID 17129372, 2006). "In the past few years, O-linked carbohydrate antigens, such as mucin antigen (MUC1), carcinoembryonic antigen (CEA), sialyl LewisX (SLX), CA19-9, Sialyl Tn (STn), and Tn have been reported to be associated with altered adhesion, invasion, recurrence, and prognosis in lung cancer and other tumours." (PMID 14735190, 2004). "It has been proposed that enhanced levels of MUC1 expression by cancer cells may mask extracellular domains from immune surveillance, confer a survival advantage on malignant cells and play an important role in the ability of tumours to invade and metastasise." (PMID 15599383, 2004).
tumor (continued). "In addition, a mucin antigen such as MUC1 inhibits the E-cadherin-mediated cell–cell adhesion, which implies that MUC1 mucin enables adenocarcinoma cells to be detached readily from the primary tumour tissue." (PMID 14735190, 2004). "Natural B-cell responses to lactation- or tumour-associated glycoforms of the mucin, as detected in women after pregnancy or in some cancer patients, improve survival rates, but usually do not eliminate the MUC1+ tumour cells in vivo." (PMID 12966437, 2003). "MAL and MUC1 showed an antagonistic relationship in cancer cells, and these findings provide new insights with respect to the regulation of MUC1 and a better understanding of MAL as a potential tumor suppressor." (PMID 42038033, 2026). "When MUC1 peptide and TLR agonists were encapsulated in C3-liposomes and used to vaccinate mice, the sex differences in tumor growth were unexpected." (PMID 40284463, 2025). "Tumor-related messenger RNAs (mRNAs), such as TK1 mRNA, MUC1 mRNA, GalNAC-T mRNA, C-myc mRNA, and survivin mRNA, have been suggested as specific biomarkers for tumor progression and prognosis." (PMID 40942076, 2025). "A previous study demonstrated the efficacy of an mRNA vaccine targeting MUC1 delivered via a lipid-based carrier in a TNBC model, reporting enhanced tumor-specific immune responses and inhibition of tumor growth." (PMID 40943370, 2025). "Selective binding to the tumor cells was assessed using four tumor cell lines including A549 and MCF-7 that overexpress the MUC1 protein and MRC-5 and MCF-10A that exhibit low MUC1 protein." (PMID 40236567, 2025). "Therapeutic cancer vaccines aim to stimulate tumor-specific immune responses and are being explored in PDAC as whole-cell (e.g., GVAX), peptide-based (e.g., GV1001, MUC-1), and dendritic cell-based vaccines." (PMID 40806185, 2025). "Flow cytometry revealed a notable increase in tumor-infiltrating CD8+ T cells (p < 0.01), and ELISPOT assays showed elevated IFN-γ production upon MUC1-specific stimulation." (PMID 40943370, 2025). "These tumours frequently retained positive staining for MUC-1, MUC-2, SATB2 and TFF-3, suggesting that these tumours maintain some degree of intestinal differentiation." (PMID 40935920, 2025). "The HMucBOT-1 tumor expressed the epithelial markers CK7, PAX8, and MUC1 in the borderline lesions; in addition, these markers were expressed in cell lines." (PMID 40427213, 2025). "Several CAR-T cell therapies are targeting EGFR, MUC1, and mesothelin (MSLN), and other tumor antigens and are being tested in early-phase clinical trials." (PMID 41373672, 2025). "As many cancer cells thrive in a hypoxic environment, the increase in MUC1 expression helps induce the increase in VEGF, connective tissue growth factor (CTGF), and platelet-derived growth factor (PDGF-β) to support tumor angiogenesis." (PMID 40699805, 2025). "New molecules and vaccines: Peptide vaccines against HER2-low and MUC1, a CSF1R inhibitor (altering the tumor microenvironment), and STING agonists are being investigated in clinical trials." (PMID 41150754, 2025). "TAAs are usually overexpressed in tumor cells, typically including carcinoembryonic antigen (CEA), prostate-specific antigen (PSA), alpha-fetoprotein (AFP), cancer antigen 125 (CA125), and mucin 1 (MUC1)." (PMID 39789208, 2025). "Several studies have highlighted the crucial role of C1GALT1‐mediated O‐glycosylation in regulating the surface localization and stability of transmembrane glycoproteins such as MUC1, CD44, and IL‐6 receptor, thereby impacting tumor growth and metastasis." (PMID 39844613, 2025). "Among the genes with significant differences, NAPSA, MUC1, WFDC2, and MYO6 were well correlated with Tumor_C1 and Unknow_C2 (cells with a high positive rate of tumor markers), and these two cell clusters were all cells with a high positive rate of PD-L1." (PMID 39991571, 2025).
tumor (continued). "The proposed method exhibited excellent analytical performance with detection limits of 0.18 ng/mL for MUC1, 3.18 ng/mL for CEA, and 1.26 ng/mL for CA125, demonstrating its potential for clinical diagnostics and multiplexed tumour marker detection." (PMID 40363817, 2025). "Mucins, including MUC1 and MUC16, are overexpressed in various gastrointestinal cancer types, and one of the key mechanisms by which they promote tumor survival is through immune evasion, effectively providing “protection” from immune cell-mediated killing." (PMID 41383589, 2025). "MUC1-CAR-T cells have demonstrated significant target-specific cytotoxicity both in vivo and in vitro, effectively inhibiting tumor growth." (PMID 41409286, 2025). "Based on the expression of key marker genes-MUC1 (tumor region), LYZ (immune region), COL14A1 (stromal region), and SFTPC (normal region)—we classified the niches into tumor, immune-stromal, and normal regions across all spatial transcriptomic samples." (PMID 40396179, 2025). "Notably, three different types of glycoepitopes (glycan-only, glycopeptide, and shielded-peptide) expressed on tumor-specific MUC1, MUC5AC, and MUC16 can be recognized by monoclonal antibodies (mAb) and may serve as promising candidate target for anticancer ADC development." (PMID 39923010, 2025). "In a study, concentrations of circulating tumour-derived EVs expressing B7H3/CD276, Mucin-1 (MUC1), and EpCAM in DTC compared to HCs, all three are epithelial tumour markers known to be overexpressed in TC." (PMID 41193833, 2025). "In the context of CMTs, biomarkers such as mucin 1 (MUC1), cytokeratins 8 and 18 (CK8/18) and Kiel 67 (Ki-67) are essential for confirming the epithelial origin of the tumour cells and evaluating their proliferative potential." (PMID 40144054, 2025). "The TAAs EpCAM, TROP2, and MUC1 showed the highest and most consistent expression across five PDAC cell lines and 14 primary tumor samples." (PMID 40358156, 2025). "In this case, we analyzed the expression of tumor cells by various IHC methods and special stains, with a review of the literature, the cytokeratin 7 (CK7) and mucin 1 (MUC-1) expression patterns of IP tumor cells contribute to pathological diagnosis." (PMID 40013097, 2025). "RT can also increase the expression of CAR-T target antigens, such as MUC-1 or CEA, on tumour cells, improving their recognition by CAR-T cells." (PMID 40906384, 2025). "In contrast, cytoplasmic MUC1 positivity in solid structures did not associate with any clinicopathological factors, and the sole association of higher membranous MUC1 staining in solid structures was with the tumor having a non‐infiltrating (i.e., pushing) border." (PMID 41332218, 2025). "Therefore, targeting STAT3 and MUC1 interplay may be a strategy for enhanced anti-tumor efficacy." (PMID 40001578, 2025). "Other CAR T targets under clinical evaluation include EGFR [NCT02980315], MUC1 [NCT03013712], CD44v6 [NCT04729543, NCT04097301], PD-L1 [NCT05117138], and CSPG4 [NCT06096038], reflecting efforts to overcome tumor heterogeneity and immune evasion." (PMID 40940995, 2025). "Male mice required the combination of MUC1 antigen and TLR agonists to establish significantly reduced tumor growth compared to PBS mice." (PMID 40284463, 2025). "By focusing on MUC1, CAR-T cells can eliminate tumor cells while sparing healthy tissue, offering a more precise and safer approach to cancer therapy." (PMID 40312353, 2025). "Overexpression of MUC1 inhibits adhesion while activating downstream signaling pathways like ERK1/2 and NFκB to control tumor migration and development." (PMID 39755633, 2025).
tumor (continued). "MUC1 can also stabilize the expression of HIF1A and increase glycolytic flux in cancer cells to reduce the sensitivity of tumor tissue to anti-tumor drugs." (PMID 38702644, 2024). "As MUC1 is a tumor target with complex attributes, including a very large size and numerous tandemly repeated epitopes that could be located both near and far from the tumor cell surface, we also aimed to better understand how various properties of the antigen affect anti-tumor antibody efficacy." (PMID 39449327, 2024). "Studies show that MUC1 is abnormally overexpressed in PCa, BCa, and RCC, and plays an important role in tumor progression." (PMID 39491020, 2024). "The current study aimed to evaluate the expression of circulating tumor markers CK20 and MUC1 in peripheral blood samples from GC patients by qRT-PCR." (PMID 38324850, 2024). "The aim of including IL-2 together with aMUC1aCD3 in TILT-322 is to generate anti-tumor immune responses by accelerating effector CD8+ T and helper CD4+ T cell proliferation in Mucin1 (MUC1)-positive tumors." (PMID 38910324, 2024). "The DC vaccines were pulsed with Wilms’ tumor gene 1 (WT1) and/or mucin 1 (MUC1) synthetic peptides, used as tumor antigens in the six participating institutions." (PMID 39308861, 2024). "The roles and potential of MUC1 and MUC16 in tumor immunotherapy research have garnered widespread attention, especially their application as biomarkers in various cancer treatment strategies." (PMID 38361923, 2024). "In another study, CAR-T was demonstrated to recognize the rare glycol-Tn antigen on MUC1 and thus mediate an excellent antitumor activity in a PDAC-loaded murine tumor model." (PMID 38434964, 2024). "We found that FGF7+/THBS1+ myofibroblasts, MS4A4A+ macrophages, and ZEB1+ endothelial cells were tumour‐enriched cell subtypes in MCA, contributing to MCA progression through crosstalk with MUC1+ cancer cells." (PMID 38778448, 2024). "The high expression of tumor-related genes (EPCAM, CD24, CDH1, ELF3, KRT18, KRT19, KRT8, and MUC1) in groups 10 and 11 suggests that cells in these groups are tumor cells." (PMID 38693422, 2024). "EGFRvIII/Anti-Tn-MUC1 CAR-T cells demonstrated specific recognition and targeted killing of tumor cells to inhibit tumor growth." (PMID 38918817, 2024). "MUC1 and MUC4, which were highly expressed on the surface of tumor cells, were also downregulated in the P. gingivalis‐treated group." (PMID 37666495, 2024). "MUC1 was expressed in TNBC cell lines as a metabolic regulator in TNBC and promotes metabolic reprogramming of glutamine utilization that affects TNBC tumor growth." (PMID 38329441, 2024). "Exploring an alternative target, a pilot study (NCT03525782) investigates the combined use of MUC1 CAR T cells with PD-1 knock-out T cells, revealing efficacy in primary tumor reduction." (PMID 38903504, 2024). "In gastrointestinal tumor research, studies on MUC1 and MUC16 are crucial in unveiling tumor immune evasion mechanisms and progression." (PMID 38361923, 2024). "CAR T cells effectively targeted MUC1, a TAA closely related to tumour progression and therapeutic response, leading to durable and specific immune cytotoxicity in MUC1+ organoids but not MUC1− organoids." (PMID 39245957, 2024). "First, the number of patients is small; second, we just evaluated two circulating tumor markers, CK20 and MUC1; and third, we examined total peripheral blood." (PMID 38324850, 2024). "Anti-Tn-MUC1 CAR-T cells reportedly showed specific targeted cytotoxicity and anti-tumor efficacy in T cell leukemia and pancreatic cancer xenograft models." (PMID 38725856, 2024). "In summary, through a generalizable pipeline for screening TAAs by single-cell transcriptomic and IHC analysis, MUC1 was selected as a candidate target to combine with EGFR, as to increase the tumor specificity over normal cells." (PMID 39664199, 2024).